GRM8 (glutamate metabotropic receptor 8)
Description:
G protein-coupled receptor for glutamate. Ligand binding causes a conformation change that triggers signaling via guanine nucleotide-binding proteins (G proteins) and modulates the activity of down-stream effectors, such as adenylate cyclase. Signaling inhibits adenylate cyclase activity.
Synonyms: mGluR8; GPRC1H; GLUR8; mGlu8
Tractability: Small molecule: a structure with a bound ligand is known; a high-quality ligand is known; it belongs to a druggable protein family. Antibody: its Gene Ontology location is reachable by antibodies, with high confidence; UniProt places it where antibodies can reach, with medium confidence; UniProt predicts a signal peptide or a membrane-spanning region. PROTAC: UniProt records ubiquitination sites on it; a small molecule that binds it is known.
Target class: Family C G protein-coupled receptor; Metabotropic glutamate receptor; Small molecule receptor (family C GPCR); Membrane receptor; Neurotransmitter receptor (family C GPCR)
Chemical probes: VU 0422288, VU0155094
Gene: Protein-coding gene on chromosome 7 (126,438,598 to 127,253,093, reverse strand). Ensembl gene ENSG00000179603.
Subcellular location: Cell membrane
Pathways (Reactome):
Signal Transduction: Class C/3 (Metabotropic glutamate/pheromone receptors); G alpha (i) signalling events
Gene Ontology:
Molecular function: G protein-coupled receptor activity; glutamate receptor activity; group III metabotropic glutamate receptor activity
Biological process: adenylate cyclase-inhibiting G protein-coupled glutamate receptor signaling pathway; adenylate cyclase-inhibiting G protein-coupled receptor signaling pathway; G protein-coupled glutamate receptor signaling pathway; regulation of synaptic transmission, glutamatergic; visual perception; G protein-coupled receptor signaling pathway
Cellular component: plasma membrane; membrane
Genetic constraint (gnomAD): Loss-of-function variants: 31 observed, 60.88 expected, observed/expected ratio (o/e) 0.51, 90% interval 0.38 to 0.69. The upper end of that interval is the gene's LOEUF score, 0.69, which puts it in group 2 of 6, group 1 being the genes least tolerant of losing a copy. Missense variants: 865 observed, 982.21 expected, observed/expected ratio (o/e) 0.88, 90% interval 0.83 to 0.93. Synonymous variants: 341 observed, 360.77 expected, observed/expected ratio (o/e) 0.95, 90% interval 0.86 to 1.03.
Homologues: Orthologues: chimpanzee GRM8 (99% identical), rat Grm8 (99% identical), mouse Grm8 (98% identical), macaque GRM8 (98% identical), pig GRM8 (97% identical), rabbit GRM8 (97% identical), tropical clawed frog grm6 (89% identical), zebrafish grm8a (82% identical), zebrafish grm8b (81% identical), Drosophila melanogaster mGluR (46% identical). Paralogues in human: GRM4 (74% identical), GRM7 (73% identical), GRM6 (67% identical), GRM2 (43% identical), GRM3 (43% identical), GRM5 (42% identical), GRM1 (41% identical).
Diseases named in the same sentence as GRM8 in open-access papers:
GRM8 is named in the same sentence as 64 diseases in open-access papers, as found by Europe PMC text mining. Sharing a sentence is not in itself a finding about the gene and the disease. The quoted sentences say what the papers report.
schizophrenia (16 papers, 2012 to 2025). A major psychotic disorder characterized by abnormalities in the perception or expression of reality. "Previously, GRM8 rs2299472*CC was shown to be associated with schizophrenia in the Uygur Chinese population." (PMID 36980845, 2023). "Other than MS, gene variants of GRM8 have been mostly associated with psychiatric disorders, such as major depressive disorder and schizophrenia." (PMID 33661276, 2021). "GRM8, a metabotropic glutamate receptor, intricately regulates glutamate neurotransmission and has established associations with various central nervous system (CNS) disorders, including major depression, schizophrenia, and autism." (PMID 38414734, 2024). "Interestingly, knockdown of H2A.Z.1, but not H2A.Z.2, led to altered expression of several candidate genes linked to psychiatric disorders such as autism and schizophrenia (Neurexin1, Shank3, CaMK2G, Vamp7, Gsk3b, Tuba8, Grm8, etc.)." (PMID 28856239, 2017). "Moreover, GRM8 has been associated with schizophrenia in the Han Chinese population." (PMID 35562887, 2022). "We examined the association of 39 single nucleotide polymorphisms in eight genes (GRIN2A, GRIN2B, SLC1A2, SLC1A3, SLC17A7, GRM3, GRM7, and GRM8) involved in the glutamatergic system with the development of clinical heterogeneity of schizophrenia." (PMID 36980845, 2023). "GRM8, like DOC2A, has been linked to schizophrenia in addition to sporadic Creutzfeldt–Jakob disease risk." (PMID 30867560, 2020). "In our study, schizophrenia patient carriers of the GRM8 rs2299472*C allele had lower scores on the Negative Subscale of PANSS." (PMID 36980845, 2023). "In a genetic study, one susceptibility locus for schizophrenia was identified within the GRM8 region in Japanese, suggesting that mGluR8 may have a therapeutic potential." (PMID 22942876, 2012). "This study indicates the likely contribution of the GRIN2A, GRIN2B, GRM8, SLC1A2, and SLC17A7 genes to the development of clinical heterogeneity in schizophrenia." (PMID 36980845, 2023). "GRM8 is a further group III mGluR and a schizophrenia candidate gene." (PMID 36980845, 2023). "In the present study, we were able to detect the contribution of the GRIN2A, GRIN2B, GRM8, SLC1A2, and SLC17A7 genes of the glutamatergic system to determining the clinical heterogeneity of schizophrenia, which is important for the prognosis and outcome of the disease." (PMID 36980845, 2023).
breast carcinoma (7 papers, 2020 to 2025). "Another member of the mGluR family, GRM8, was shown to function as an oncogene in breast cancer and was linked to a worse overall survival rate." (PMID 36139432, 2022). "The results showed that GRM8 expression was increased in breast cancer tissues and cells, which was closely associated with lower overall survival rate." (PMID 34950209, 2021). "To explore the molecular mechanism underlying GRM8 in breast cancer progression, we used bioinformatics to search the predicted regulatory miRNAs of GRM8." (PMID 34950209, 2021). "However, studies identified activating mutations in GRM8, implicating its involvement in the pathogenesis and progression of several malignancies, including neuroblastoma, lung cancer, glioma, and breast cancer." (PMID 40083231, 2025). "It has been reported that glutamate metabotropic receptor 8 (GRM8) is closely implicated in the progression of human neuroblastoma, lung cancer, and glioma, but its role in breast cancer remains unknown." (PMID 34950209, 2021). "The GRM8 gene is a breast cancer oncogene, and its expression is known to inhibit glioma tumor cell proliferation." (PMID 39387520, 2024). "Compared with the adjacent normal tissues, the expression of GRM8 was significantly elevated in breast cancer tissues at mRNA and protein levels." (PMID 34950209, 2021). "Herein, we focused on the role and mechanism of GRM8 in breast cancer progression for the first time, and the results demonstrated that GRM8 was significantly overexpressed in breast cancer, which predicted poor prognosis." (PMID 34950209, 2021). "To explore GRM8 role in the progression of breast cancer, we first assessed its expression profiles in breast cancer tissues and cells through RT-PCR, western blotting, and/or IHC technology." (PMID 34950209, 2021). "In the present study, we aimed to explore GRM8 effect on the progression of breast cancer, as well as to reveal the relationship between miR-33a-5p and GRM8, and the role of miR-33a/GRM8 axis in breast cancer progression." (PMID 34950209, 2021). "Then, we explored the relationship between miR-33a-5p and GRM8 in breast cancer HCC1937 and SK-BR-3 cells." (PMID 34950209, 2021). "Collectively, this study reveals that GRM8 functions as an oncogene in breast cancer and is regulated by miR-33a-5p." (PMID 34950209, 2021). "Collectively, the present study discloses that GRM8, negatively regulated by miR-33a-5p, functions as an oncogene in breast cancer progression." (PMID 34950209, 2021). "It was demonstrated that GRM8 is negatively regulated by miR-33a-5p in breast cancer." (PMID 36139432, 2022). "Our study indicates the important role that miR-33a-5p/GRM8 axis plays in breast cancer progression, which might be a potential treatment target in breast cancer." (PMID 34950209, 2021). "However, GRM8 expression level was significantly higher in breast cancer cells than normal breast cells; thus, we think the GRM8 targeting therapy should be designed by higher affinity with breast cancer cells than normal cells in the future." (PMID 34950209, 2021). "Then, we explored GRM8 role in breast cancer progression through in vitro experiments." (PMID 34950209, 2021). "Moreover, overexpression of GRM8 abrogated the inhibitive role of miR-33a-5p played in breast cancer." (PMID 34950209, 2021). "Similarly, GRM8 showed an increased expression pattern in breast cancer cell lines, including HCC1937, Bcap-37, MDA-MB-231, MCF7, and SK-BR-3 as compared to that of the normal breast Hs 578Bst cells." (PMID 34950209, 2021). "In addition, GRM8 was under the negative regulation of miR-33a-5p, which was downregulated in breast cancer tissues and served as a tumor suppressor." (PMID 34950209, 2021). "Then, we explored miR-33a-5p/GRM8 axis in the progression of breast cancer." (PMID 34950209, 2021). "Moreover, we confirmed that miR-33a-5p served as a tumor suppressor in breast cancer through binding to GRM8." (PMID 34950209, 2021).
breast carcinoma (continued). "The Kaplan–Meier curve showed that patients with GRM8 high expression had a lower overall survival rate than that of patients with GRM8 low expression, suggesting that the high expression of GRM8 predicted a poor outcome of patients with breast cancer." (PMID 34950209, 2021). "In addition, we assessed GRM8 role in regulating breast cancer cell migration and invasion." (PMID 34950209, 2021). "However, whether miR-33a-5p targets GRM8 and then involves in the progression of breast cancer remains unclear." (PMID 34950209, 2021). "The expression of GRM8, SPC25, and FAM72A was negatively correlated with favorable outcomes and also observed in other cancer types such as lung cancer and breast cancer." (PMID 35368665, 2022). "In addition, GRM8, under the negative modulation of miR-33a-5p, functioned as an oncogene in the progression of breast cancer." (PMID 34950209, 2021).
epilepsy (7 papers, 2015 to 2025). A brain disorder characterized by episodes of abnormally increased neuronal discharge resulting in transient episodes of sensory or motor neurological dysfunction, or psychic dysfunction. "Yet, the most prominent genes in the IESS condition, Grm8 (male) and Mapk10 (female), have documented implications in epilepsy." (PMID 40699779, 2025). "These microdeletions affected 158 protein-coding RefSeq genes and exhibited an enrichment of genes previously associated with epilepsy (NRXN1, RBFOX1, PCDH7, KCNA2, EPM2A, RORB, PLCB1) and neuropsychiatric disorders (DPYD, CADM2, PARK2, GRM8, TSNARE1, TPH2, MACROD2)." (PMID 25950944, 2015). "In addition, the reduced expression of Grm7 and Grm8 that we found in all studied regions may also contribute to epilepsy development." (PMID 35269897, 2022).
Anxiety (6 papers, 2017 to 2025). Intense feelings of nervousness, tension, or panic often arise in response to interpersonal stresses. "In accordance, behavioral studies of mice that are deficient in Grm8 showed higher levels of anxiety." (PMID 33661276, 2021). "Genetic deletion of Grm8 is also associated with alterations in fear- and anxiety-like behavior." (PMID 31164799, 2019). "Therefore, our zebrafish grm8b model may be useful in elucidating the mechanism behind anxiety-like behavior associated with reduced Grm8 activity." (PMID 35769333, 2022). "Both Grm8 and Asic1 are thought to play a role in modulating stress-related emotional traits such as fear and anxiety." (PMID 31164799, 2019).
autism (6 papers, 2012 to 2024). Persistent deficits in social interaction and communication and interaction as well as a markedly restricted repertoire of activity and interest as well as repetitive patterns of behavior. "Several candidate autism susceptibility genes were hypermethylated (P <0.05) in the HMFA, including Shank3, Cacana1g, Gtf2i, Rapgef4, and Nbea in male offspring and Ext1, Ube3a, Erbb4, Grip1, Grm8, Reeln, Shank3, and Rbfox1 in female offspring." (PMID 24484737, 2014).
depression (6 papers, 2018 to 2025). "There is a linkage to and an association between theta-event-related oscillations (EROs) and targets in the visual oddball task and SNPs in GRM8 (the metabotropic glutamate receptor gene) that were also found to be associated with alcohol dependence and related phenotypes (e.g., depression)." (PMID 40149928, 2025). "In addition, data collected from the gene Grm8, which encodes mGluR8, indicates that the receptor plays a crucial role in depression-related pathways." (PMID 36499434, 2022). "GRM8 is involved in the inhibition of the cyclic AMP cascade influencing glutamatergic neurotransmission and had an association with depression (P = 1.80 × 10−12) in a genome-wide association meta-analysis." (PMID 34523677, 2022).
lung carcinoma (6 papers, 2017 to 2025). "These two reports suggest that GRM8 functions as a tumor suppressive gene in human neuroblastoma, glioma, and lung cancer." (PMID 34950209, 2021). "CRISPR technology has been successfully applied to implement the editing and modulation of numerous oncogenes such as epidermal growth factor receptor (EGFR), KRAS, focal adhesion kinase (FAK), metabotropic glutamate receptor 8 (GRM8), SMAD3/4, and MET in lung cancer." (PMID 38188023, 2023).
neuroblastoma (5 papers, 2021 to 2025). Neuroblastoma (NB) is the most common solid, extracranial childhood tumor. "By contrast, GRM8 is an appealing drug target, as it is predominantly expressed in neurons and its activation has been reported to protect undifferentiated neuroblastoma cells against doxorubicin and the mitochondrial toxin MPP4+." (PMID 33661276, 2021). "It should be noted that GRM2, GRM7 and GRM8 are the mGluR genes that showed the highest expression values in our SK-N-SH cells, which is in accordance with data reported in SH-SY5Y neuroblastoma cells." (PMID 36768378, 2023).
squamous cell lung carcinoma (4 papers, 2021 to 2024). A carcinoma arising from squamous bronchial epithelial cells. "Gene mutations observed differ between lung adenocarcinoma and lung squamous cell carcinoma, with KRAS, EGFR, LPHN3, KEAP1, and TLR4 being relatively common in lung adenocarcinoma, whereas BAI3, FBXW7, GRM8, ERBB4, MUC16, and RUNX1T1 are common in lung squamous cell carcinoma." (PMID 39594843, 2024).
autism spectrum disorder (3 papers, 2014 to 2022). A spectrum of developmental disorders that includes autism, and Asperger syndrome. "GRM6 and GRM8, the paralogs of GRM7, have been implicated in neurodevelopmental diseases such as attention deficit hyperactivity disorder (ADHD) and autism spectrum disorders (ASD)." (PMID 27435318, 2016). "A partial duplication of the GRM8 gene has been discovered in an individual with autistic spectrum disorder." (PMID 24649381, 2014).
Alcoholism (2 papers, 2013 to 2025). "Interestingly, electrophysiological studies linked variants within GRM8 to increased risk of vulnerability to alcoholism." (PMID 24392270, 2013). "The metabotropic receptor GRM8 has been associated with smoking behavior and liability to alcoholism implying there may be a role in addiction vulnerability." (PMID 24392270, 2013).
Creutzfeldt-Jakob disease (2 papers, 2018 to 2020). "Specifically, protein metabotropic glutamate receptor mGluR8 (Grm8) associates with heightened Creutzfeldt-Jakob disease risk and was found here to be putative target genes for miR-342-3p." (PMID 32549330, 2020). "Increased expression of mGlu8 in microglia was suggested in patients with sporadic Creutzfeldt-Jakob disease with a risk allele containing a GRM8 genetic variant." (PMID 30072879, 2018).
heroin addiction (2 papers, 2012 to 2020). "A genome-wide association approach has identified Grm8, the gene encoding mGluR8, as having a strong association with heroin addiction." (PMID 22942876, 2012).
nicotine dependence (2 papers, 2012 to 2018). Physical and psychological dependence on nicotine. "Both GRM7 and GRM8 are part of the glutamate signaling pathway and were previously reported to be associated with nicotine dependence and smoking initiation respectively." (PMID 23227220, 2012). "For example, GRM7 in chromosome 3p26.1 and GRM8 in chromosome 7q31.33 are important in the biological processes and development of nicotine dependence, and some of these risks may be shared across diverse population." (PMID 30104567, 2018).
adenoma (1 paper, 2016). A neoplasm arising from the epithelium. "GRM8 and LY6G6D/F were differentially expressed by this method, but had high percentages of expression in normal colon, i.e. were less able to distinguish CRC from normal tissues, these markers scored 26% and 36% ≥4 in normal colon tissue respectively, compared to 63% and 88% ≥4 for adenomas." (PMID 26894861, 2016).
Cirrhosis (1 paper, 2023). A chronic disorder of the liver in which liver tissue becomes scarred and is partially replaced by regenerative nodules and fibrotic tissue resulting in loss of liver function. "Protein products of the EDG4, CCL20, GPR109A, and GRM8 genes, whose CpG sites are characterized by changes in DNA methylation level in tumor tissue in the setting of cirrhosis and fibrosis, belong to “Signaling by G-protein-coupled receptors (GPCRs)” category." (PMID 36923478, 2023).
colon cancer (1 paper, 2016). "Protein expression generally did not correspond to mRNA expression for the remaining markers, i.e. GRM8, LY6G6D/F, SLCO1B3 and TLR4, indicating that protein levels for these markers are likely regulated after translation in this set of colon cancer cells." (PMID 26894861, 2016).
cutaneous melanoma (1 paper, 2016). A primary melanoma arising from atypical melanocytes in the skin. "The Cancer Genome Atlas (TCGA) Network reported 224 gene fusions in 333 cutaneous melanomas with a recurrent GRM8-CNTNAP2 fusion in two tumors." (PMID 26909863, 2016).
endometrial cancer (1 paper, 2020). Primary or metastatic malignant neoplasm involving the endometrium (mucous membrane that lines the endometrial cavity). "GRM8 is a tumour-suppressor gene in endometrial cancer cell lines." (PMID 33344083, 2020).
Insulin resistance (1 paper, 2021). Increased resistance towards insulin, that is, diminished effectiveness of insulin in reducing blood glucose levels. "Grm8 deficiency in mice resulted in mild insulin resistance and weight gain." (PMID 33661276, 2021).
lymph node metastasis (1 paper, 2018). "Here, 186 upregulated (e.g., GSR, HCP5) and 144 downregulated DEGs (e.g., MET, GRM8, and DACH1) were identified between the SCLC patients with lymph node metastasis and without lymph node metastasis." (PMID 30364292, 2018).
mental disorder (1 paper, 2021). A disease that has its basis in the disruption of mental process. "GRM8 encodes MGLUR8, a G-protein coupled glutamate receptor reported to significantly influence the risk of diseases affecting the CNS including behavior, mental disorder, cognition as well as tumorigenesis of the CNS and other systems." (PMID 33816256, 2021).
non-small cell lung carcinoma (1 paper, 2014). A group of at least three distinct histological types of lung cancer, including non-small cell squamous cell carcinoma, adenocarcinoma, and large cell carcinoma. "High-throughput genomic studies have identified GRM1, GRM3, GRM4, GRM8 and GRIN2A as susceptibility genes in non-small-cell lung cancer (NSCLC), melanoma, osteosarcoma, and bladder cancer." (PMID 25326682, 2014).